AIRN (antisense of IGF2R non-protein coding RNA)
Synonyms: AIR; NCRNA00088; IGF2RAS; IGF2R-AS1; IGF2R-AS
Gene: Long non-coding RNA gene on chromosome 6 (160,002,409 to 160,007,664, reverse strand). Ensembl gene ENSG00000268257.
Diseases named in the same sentence as AIRN in open-access papers:
AIRN is named in the same sentence as 3 diseases in open-access papers, as found by Europe PMC text mining. Sharing a sentence is not in itself a finding about the gene and the disease. The quoted sentences say what the papers report.
breast carcinoma (1 paper, 2025). "AIRN, a genomically imprinted lncRNA, is another lncRNA that is overexpressed in circulating NK cells isolated from peripheral blood of breast cancer patients with fold change of 7.97, P = 0.0379." (PMID 40781182, 2025). "Similar to HOTAIR, AIRN recruits the histone modifying complex PRC2 potentially mediating gene silencing in NK cells and affecting its antitumor activity in breast cancer patients." (PMID 40781182, 2025).
liver fibrosis (1 paper, 2022). "Moreover, total RNAs were isolated from the serums of 47 patients with liver fibrosis and found that the level of AIRN was increased in these patients compared with 30 healthy volunteers." (PMID 36171606, 2022).
AIRN also shares sentences with these, for which no sentence is quoted: hepatocellular carcinoma (1 paper).